IL6 (interleukin 6)
Diseases named in the same sentence as IL6 in open-access papers (continued):
Sharing a sentence is not in itself a finding about the gene and the disease.
knee osteoarthritis (continued). "Similarly, we previously observed significant associations between the endo-EV and exo-EV concentrations of TNF-α, IL-6, and IFN-γ in plasma of patients with knee osteoarthritis, but not IL-1β." (PMID 38633262, 2024). "As our study showed a lower level of Gal-3 as well as TNF-α, IL-6, IL-12, IFN-γ, and IL-17 in gonarthrosis patients with DM, we believe that the lack of these cytokines caused intense tissue damage and slower tissue repair, which is reflected through a higher WOMAC score." (PMID 36141752, 2022).
leprosy (43 papers, 2009 to 2025). Leprosy is a chronic infectious disease affecting primarily the skin and peripheral nervous system. "Elevated levels of interleukin (IL)-10, IL-6, and leptin have been associated with helminth infection and leprosy, respectively." (PMID 41239264, 2025). "The increased Th2 regulation in leprosy patients with helminth infections is considered to be the cause of raised IL-10 and indirectly also increases IL-6 levels in leprosy with helminth infections compared to those without helminth infections." (PMID 41239264, 2025). "TNF is able to regulate the expression of IL-6 and together enhance the inflammation process of nerve cells, causing neuritis in leprosy reactions." (PMID 38381878, 2024). "The present study for the first time establishes that pathogenic Th17 cells produce IL-17 in an IL-6 dependent manner in leprosy T1R reactions." (PMID 32934336, 2020). "The polymorphism of IRGM rs13361189 was found to be related to leprosy by affecting the production of IL-4, IL-6, and INF-γ." (PMID 29992164, 2018). "IL6 has been previously associated with leprosy reactions in other populations and by using different study designs." (PMID 28715406, 2017). "From the results, we conclude that SNPs at the NOD2 and IL6 genes are associated with leprosy reactions as an outcome." (PMID 28715406, 2017). "IL-6 is a pro-inflammatory cytokine produced in highconcentrations in leprosy and associated with the development of ENL." (PMID 28327786, 2017). "In addition, clinical studies have shown that single-nucleotide polymorphisms (SNPs) in the IL-6 gene are associated with leprosy reactions." (PMID 35281455, 2022). "However, the most interesting aspect of these experiments was that the same alleles in the same SNPs impacted both CCL2 and IL6 transcript levels and susceptibility to leprosy." (PMID 23350010, 2013). "Taken together, the present results provide an example of how genetic risk factors of leprosy may impact on leprosy pathogenesis by modulating the production of IL-6 and MCP-1, two key host response mediators." (PMID 23350010, 2013). "The synergetic effect of down regulated TGF-β and upregulated IL-6 in both reactions may play an important role in the balance of Treg and Th17 cell differentiation and thereby lead to the immunopathology associated with leprosy reactions." (PMID 32934336, 2020). "For leprosy with helminth infection, the mean IL-10, IL-6, and leptin serum levels were 86.43 pg/ml ± 4.34 pg/ml, 447.42 pg/ml ± 122.15 pg/ml, and 19,272.85 pg/ml ± 4,065.23 pg/ml, respectively." (PMID 41239264, 2025). "Serum levels of IL-10, IL-6, and leptin are known to be raised in leprosy patients and in helminth infection patients, respectively." (PMID 41239264, 2025). "In this study, the average IL-10, IL-6, and leptin serum levels in leprosy patients with helminth infections were higher than those without helminth infection." (PMID 41239264, 2025). "Leprosy patients with helminth infections have considerably greater serum levels of IL-10 and IL-6, suggesting that helminth infection influences leprosy patients’ immunological responses." (PMID 41239264, 2025). "Toll-like receptors (TLR) 1, TLR2, TLR4, dendritic cell-specific intercellular adhesion molecule-3-grabbing non-integrin (DC-SIGN), and CD163 mediate the interaction between macrophages and M. leprae in leprosy, which increases IL-6 and IL-10 secretion." (PMID 41239264, 2025). "Cytokines level before the introduction of vaccination suggested that leprosy cured group have relatively high concentration of IL-6, IL-10, TNF, INF-γ and IL-17 compare to control group." (PMID 34397815, 2021). "We also identify IL-6 and IL-17 as 2 sensitive indicators of immune response in leprosy cured patients." (PMID 34397815, 2021). "At day 0, leprosy cured group have relatively high concentration of interleukin-6, interleukin-10, tumor necrosis factor, interferon-γ, and interleukin-17 compared to control group." (PMID 34397815, 2021).
leprosy (continued). "Interleukin-6 and interleukin-17 were 2 sensitive indicators in immune response for leprosy affected patients." (PMID 34397815, 2021). "Subsequently, consistent with our previous findings in patients with T1R leprosy, we found IL-6R and IL-6 expression in stimulated PBMC cells, correlated with the Th17 response in T1R." (PMID 32934336, 2020). "Subsequently, our group also showed that IL-6 induces Th17 cell differentiation along with TGF-β in leprosy reactions." (PMID 32934336, 2020). "In the present study, using IL-6 receptor (IL-6R)-blocking antibody, we examined the effects of IL-6 blockade on leprosy reactions, in light of Th17 cell differentiation." (PMID 32934336, 2020). "Cox models showed associations between the SNPs rs751271 at NOD2 and rs2069845 at IL6 with leprosy reactions (HRGT = 0.45, p = 0.002; HRAG = 1.88, p = 0.0008, respectively)." (PMID 28715406, 2017). "We identified higher serum IL-1, IL-6, and IL-10 levels in individuals with leprosy and dental infection compared with individuals with leprosy without dental infection." (PMID 26339136, 2015). "Among the common proinflammatory mediators identified in serum during the occurrence of leprosy reactions (a) and PD (b), IL-6 and TNF-α were predominant." (PMID 26339136, 2015). "In a case–control study was observed a correlation between plasma levels of IL-6 and IL6 genotypes in patients with Type-2 reactions in leprosy." (PMID 26793196, 2015). "Taken together our data supports the greater role of IL-23 and its ligand IL-23R in leprosy as compared to IL-6/IL-6R for IL-17 production in both circulating cells and at the site of the dermal lesions." (PMID 23936569, 2013). "In a final set of experiments we found that genetic risk factors of leprosy located in the PARK2 promoter region were significantly correlated with M. leprae sonicate triggered CCL2 and IL6 transcript levels in whole blood assays." (PMID 23350010, 2013). "This survey of circulating cytokines has identified elevations in CXCL10 and IL6 as promising markers for leprosy T1R." (PMID 19473542, 2009). "An elevated level of IL-4, IL-6, and IL-8 has also been reported in leprosy." (PMID 37809252, 2023). "IL-6 plays important role in inflammation and activation of Th1 and Th17 cells, which are involved in controlling M. leprae infection and thereby influence the clinical manifestations of leprosy." (PMID 36972292, 2023). "IL-6 also appears to play an important role in leprosy reactions." (PMID 35924037, 2022). "We further select 7 cytokines and immune mediators to detect immune response after vaccination and found that before the onset of vaccination, leprosy cured group have relatively high concentration of IL-6, IL-10, TNF, INF-γ and IL-17 compared to control group." (PMID 34397815, 2021). "Here, we investigated whether SNPs located in eleven genes: CCDC122/LACC1, IFNG, IL6, IL10, IL23R, LRRK2, NOD2, PACRG/PRKN, TLR1, TNF and TYK2 are associated to leprosy susceptibility in a population in the North of Brazil." (PMID 32433683, 2020). "IL-6 was higher in both groups with pain (leprosy and diabetic patients), and could be a therapeutic target in pain control." (PMID 32038662, 2020). "The markers included 11 SNPs selected to replicate the previously reported associations of the TLR1, NOD2, and IL6 genes and the remaining SNPs in 4 candidate genes TNF, LTA, IFNG, and IL10, in reference to markers previously associated with leprosy per se as an outcome." (PMID 28715406, 2017). "We then investigated the nature of cells producing IL-6 in four patients of each leprosy group." (PMID 27035913, 2016). "In this systematic review, we identified important pro- and anti-inflammatory mediators involved in the occurrence of dental infections and leprosy reactions, including IL-6, IFN-γ, TNF-α, IL-1β, IL-17, IL-10, and IL-4, which were independent of the laboratory technique and sample." (PMID 26339136, 2015).
leprosy (continued). "In summary, regardless of the laboratory technique used and the type of sample analyzed, the identified proinflammatory mediators involved in the immune pathologic process of dental infections and leprosy reactions, particularly IL-6 and TNF-α, were similar in the studies reviewed." (PMID 26339136, 2015). "Moreover, we demonstrate significant correlation of IL6 and CCL2 transcript levels in a whole blood assay with specific variants of PARK2 previously identified as leprosy risk factors." (PMID 23350010, 2013). "Significant associations with leprosy were observed for 8 polymorphisms (rs1800871, rs1800872, and rs1554286 of IL10, rs3171425 and rs7281762 of IL10RB, rs2228048 and rs744751 of TGFBR2, and rs1800797 of IL6)." (PMID 23936864, 2013). "Our second study on leprosy reactions demonstrated that elevated expression of IL-6 and lower TGF-β in leprosy reaction initiated synergistic effect in differentiation of Th17 cells." (PMID 32934336, 2020). "When comparing leprosy patients to HHC, 16 genes showed significantly different expression for leprosy patients (increased: FCGR1A, IL6, IL15, LRKK2, MBP, MSR1, PACRGv1, TLR1, TLR4; decreased: CAMTA, CD3E, CTLA4, CXCL13, GATA3, LAG3, TFGB)." (PMID 31784594, 2019). "We analyzed the presence of M4 macrophage markers (CD68, MRP8, MMP7, IL-6, and TNF-α) in 33 leprosy skin lesion samples from 18 patients with tuberculoid leprosy and 15 with lepromatous leprosy by immunohistochemistry." (PMID 30442123, 2018). "The source of IL-6 was found to lie in the monocyte, granulocyte population and the percentage of IL6+monocytes were increased in both types of leprosy reaction patients." (PMID 27035913, 2016). "For leprosy reactions, the most common proinflammatory mediators were TNF-α (7 articles), IFN-γ (5 articles), IL-6 (4 articles), and IL-17 (3 articles), and the most common anti-inflammatory mediators were IL-4 (4 articles) and IL-10 (4 articles)." (PMID 26339136, 2015). "Beside IFN-γ, also IP-10, IL-6, IL-1β, TNF-α, and MCP-1 were increased in EC from areas with high leprosy prevalence in response to these ML1601c peptides." (PMID 22363349, 2012). "Based on the results of statistical analysis using independent t-tests between leprosy patients with and without helminth infection, a p-value of 0.001 (p < 0.05) was obtained for serum IL-10 levels and 0.0001 (p < 0.05) for serum IL-6 levels." (PMID 41239264, 2025). "Based on an independent t-test, the difference in serum levels of IL-10 and IL-6 in leprosy patients with and without helminth infections was p = 0.001 and p = 0.0001, respectively." (PMID 41239264, 2025). "Meanwhile, the mean IL-10, IL-6, and leptin serum levels for leprosy without helminth infection were 72.97 pg/ml ± 14.69 pg/ml, 161.77 pg/ml ± 63.98 pg/ml, and 14,649.07 pg/ml ± 2,002.66 pg/ml, respectively." (PMID 41239264, 2025). "Based on the results of the statistical analysis in this study, there were significant differences in IL-10 (p = 0.001) and IL-6 (p = 0.0001) serum levels between leprosy patients with and without helminth infections." (PMID 41239264, 2025). "To ascertain if the increased levels of IL-6 would be derived from reactional episodes or neuritis we selected the serum from leprosy patients without reactional episodes or neuritis and evaluated IL-6 and TNF levels by ELISA." (PMID 34797866, 2021). "TNF and IL-6 levels were evaluated in serum samples from people affected by leprosy and UN with or without ulnar CB." (PMID 34797866, 2021). "TGF-β and IL-6 revealed opposing effects with negative correlation (r2 = -0.45, p<0.04) in stable leprosy and a positive correlation in leprosy reactions (r2 = 0.49, p<0.02)." (PMID 27035913, 2016). "The proinflammatory mediators in dental infections and leprosy reactions, especially IL-6 and TNF-α, were similar across studies, regardless of the laboratory technique and sample type." (PMID 26339136, 2015).
leprosy (continued). "In the case of leprosy, we believe that the mediators CXCL8, CCL3, CXCL10, IL-9, IL-6, and IFN-γ could be considered as potential biomarkers for the future development of rapid assays that could assist in the diagnosis and prognosis of leprosy and leprosy reactions." (PMID 40109344, 2025). "Here, we evaluated serum levels of both TNF and IL-6 in leprosy patients with or without CB." (PMID 34797866, 2021). "Consequently, we report that IL-6 is essential for the initiation of leprosy reactions, rather than its progression, through Th17 differentiation." (PMID 32934336, 2020). "Modulation of IL-6 and MCP-1 secretion via the TLR signaling cascade is a reasonable hypothesis since TLR recognition of M. leprae antigens is a well-established step in leprosy pathogenesis." (PMID 23350010, 2013). "Indeed, the increase in TNF, IL-1β, IL-6, MCP-1, and MIP-1β mediators typically produced by monocytes supports the idea of BCG-induced “trained immunity” as a Th1/Th17 heterologous mediating mechanism of immune activation favoring disease protection of HC of leprosy patients." (PMID 28467415, 2017). "Here, we confirmed the association between IL6 and NOD2 SNPs and leprosy reactions among Brazilians, and demonstrated that the NOD2 genotype associated with a decreased risk for developing a reaction is also related to lower levels of IL-6 in the sera of non-reactional patients." (PMID 28715406, 2017). "After checking the status of IL-6R+ and IL-23R+ Th17 cells in reactional states, we were next interested in the secretion status of IL-17 via Th17 cells with or without MLSA, r-IL-6, r-TGF-β and r-IL-23 in both T1R and NR leprosy patients." (PMID 32934336, 2020). "Among the articles of leprosy reactions, regardless of the type of sample, IFN-γ, TNF-α, IL-6, and IL-1β were involved in T1Rs and T2Rs." (PMID 26339136, 2015).
Osteopenia (43 papers, 2009 to 2025). Osteopenia is a term to define bone density that is not normal but also not as low as osteoporosis. "Lack of skeletal cholinergic nerve fibers causes osteocyte atrophy and osteopenia due to reduced bone formation, while increased IL-6 during exercise drives expansion of bone-anabolic cholinergic fibers." (PMID 35276096, 2022). "Patients with inflammatory diseases in whom IL-6 levels are highest may be at increased risk for osteopenia." (PMID 22474400, 2012). "IL-6 may have a role in the osteopenia associated with inflammation in vivo." (PMID 22474400, 2012). "In IL-6-overexpressed transgenic mice, osteopenia, severe alterations in bone microarchitecture, increased osteoclastogenesis, and reduced osteoblast activity were observed." (PMID 40395806, 2025). "cKO mice exhibited increased osteocytic expression of Sost, Fgf23 and senescence inducing gene Pai-1 and the senescence markers p16 and Il-6, decreased serum phosphate levels, and low-turnover osteopenia." (PMID 37198221, 2023). "In bone, most inflammatory factors (such as TNF-α, IL-1, and IL-6) can promote the function of osteoclasts, thus breaking the balance between bone formation and absorption, resulting in osteopenia." (PMID 35923245, 2022). "Among interleukins, only IL6 level was found to have significantly increased in the osteopenia group with median 12.1 (6.4-25.6) as compared to 7.5 (3.2-25.5) in the control group (p = 0.013)." (PMID 33376557, 2020). "The IL-6 signaling pathway in MM cells promotes an inflammatory bone microenvironment that results in osteopenia, increased tumor burden and disease progression." (PMID 30671025, 2018). "In vivo studies of IL-6 found that in transgenic mice with overexpressed IL-6 there is greater bone turnover, reduced osteoblasts, and increased osteoclasts leading to osteopenia." (PMID 30274530, 2018). "IL-6 transgenic mice showing chronic overexpression of IL-6 developed a severe osteopenia with reduced osteoblast and increased osteoclast numbers and activity." (PMID 21463222, 2011). "After binding with the osteocalcin receptor GPRC6A in muscle, it may influence osteopenia by promoting glucose metabolism, lipid metabolism, insulin secretion, expression and exercise-induced IL-6 secretion." (PMID 40771224, 2025). "The results showed that IL-6 is highly expressed in cartilage in AIS osteopenia." (PMID 30819183, 2019). "TNF-α, IL-1, and IL-6 also suppress differentiation of osteoblasts, which is consistent with our observation that osteoblast numbers were reduced in bones which exhibited osteopenia." (PMID 27956598, 2017). "Moreover, IL-6-overexpressed-transgenic mice appear to have osteopenia and defective ossification, in which the activity of mature osteoblasts is significantly decreased." (PMID 27128729, 2016). "Also, the treatment of rats with STZ revealed a significant increase of IL-6, glycosylated haemoglobin (HbA1c), and osteopenia detected by DEXA bone mineral density tests." (PMID 23024697, 2012). "Disuse osteopenia, periprosthetic and infection related bone loss are all associated with increases in 'pathological' osteoblast apoptosis, enhanced cell suicide mediated by proinflammatory cytokines such as TNF alpha, anti CD 95-IgM, Il-1β and Il-6." (PMID 19527527, 2009). "The possible explanation for the relationship between BMD and the incidence of HF in males can be due to the intense inflammation and high cytokine levels such as IL-6, TNF-α, and oxLDL that accompany the osteopenia in males." (PMID 38740674, 2024). "Salvianolate treatment ameliorate osteopenia and improved bone quality through increasing the Osterix, OPN, Runx2 level and decrease TNF-α, IL-6 level in serum." (PMID 36387862, 2022). "Salvianolate treatment could increase Osterix, OPN, Runx2 level and decrease TNF-α, IL-6 level in serum and IL-1β protein in TNF-α-induced MC3T3-E1 osteoblasts, finally ameliorate osteopenia and improved bone quality." (PMID 36387862, 2022).
Osteopenia (continued). "We found that in AIS osteopenia, high plasma adiponectin levels which may due to the gene variation may affect bone mass through the modulation of RANKL/OPG in osteoblasts and IL6 release in chondrocytes by binding to adipoR1." (PMID 30819183, 2019). "Additionally, it is well documented that the production of local and circulating pro-inflammatory cytokines, including TNF-α, IL6, and IL10, plays an important role in the occurrence and development of osteopenia by inhibiting osteoblast function and promoting osteoclast differentiation." (PMID 30819183, 2019).